MYC (MYC proto-oncogene, bHLH transcription factor)
Diseases named in the same sentence as MYC in open-access papers (continued):
Sharing a sentence is not in itself a finding about the gene and the disease.
choroid plexus tumours (1 paper, 2019). "We demonstrate that c-MYC is expressed in a substantial proportion of human choroid plexus tumours and that this subgroup of tumours is characterised by an inflammatory transcriptome and significant inflammatory infiltrates." (PMID 31142360, 2019). "Our data raise the possibility that benign choroid plexus tumours expressing c-MYC could be amenable to medical therapy with anti-inflammatory drugs." (PMID 31142360, 2019).
chronic hepatitis B infection (1 paper, 2025). "High-throughput sequencing has also revealed copy number variations (amplification of MYC and deletions in CDKN2A) and mutational signatures linked to aflatoxin exposure and chronic hepatitis B infection." (PMID 40869967, 2025).
clear cell ovarian cancers (1 paper, 2018). "Specifically, in clear cell ovarian cancers, RAS mutations and c-MYC amplifications are prominent in addition to PIK3CA and PTEN alterations which is expected to lead to increased tumorigenic potential associated with “iron addiction”." (PMID 29435183, 2018).
cognitive decline (1 paper, 2019). "Cognitive problems including cognitive decline and psychomotor retardation have been reported in all but 5 genetic disorders, MYC/DYT‐SGCE, MYC/DYT‐KCTD17, mUDP7 (based on loss of SGCE‐gene), DYT‐ANO3, and the hyperekplexias." (PMID 31584223, 2019).
cognitive disease (1 paper, 2025). "MYC targets are expressed early during brain development and demonstrate increased expression later in the context of traumatic brain injury or cognitive disease." (PMID 40985448, 2025).
diabetic cardiomyopathy (1 paper, 2024). Diabetic cardiomyopathy is a disorder of the heart muscle in people with diabetes. "Meanwhile, according to previous literature, EPAS1, an endothelial PAS domain protein 1, has been found to have some association with the stability of HCM; MYC is one of the top ten hub genes in diabetic cardiomyopathy (DbCM)." (PMID 38799173, 2024).
diabetic foot ulceration (1 paper, 2023). "Besides, NFKBIA affects the wound healing in diabetic foot ulceration (DFU) (p=0.006), MYC and SCD are related to pyroptosis and immune infiltration in T2DM (p=0.001)." (PMID 37293508, 2023).
Diamond-Blackfan anemia (1 paper, 2020). A congenital aregenerative and often macrocytic anemia with erythroblastopenia.
diffuse midline glioma (1 paper, 2024). A diffuse glioma that arises from the midline structures of the central nervous system. "Sulfopin inhibits MYC signaling and reduces viability of diffuse midline glioma (DMG) cells in an H3-K27M-dependent manner." (PMID 39093942, 2024).
Duchenne muscular dystrophy (1 paper, 2018). Duchenne muscular dystrophy (DMD) is a neuromuscular disease characterized by rapidly progressive muscle weakness and wasting due to degeneration of skeletal, smooth and cardiac muscle. "The DYS-HAC was transferred to Duchenne muscular dystrophy patient-derived fibroblasts from CHO cells, from which iPSCs were generated using a combination of lentiviral infection for expressing mouse SLC7A1 and retroviral infection for expressing KLF4, SOX2, OCT4, and c-MYC." (PMID 32161806, 2018).
duodenal adenocarcinoma (1 paper, 2025). A carcinoma that arises from glandular epithelial cells of the duodenum. "The HIF1α, STAT3, and MYC expression levels in duodenal adenocarcinoma were analyzed alongside their correlation with Linc01559." (PMID 40722682, 2025).
E. coli infection (1 paper, 2024). "E. coli infection in hypoxia (HE) strongly downregulates MYC Targets V1 and V2, mTORC1 signaling, E2F signaling, interferon γ response, and TGFβ signaling." (PMID 38720110, 2024).
Emery-Dreifuss muscular dystrophy (1 paper, 2019). Emery-Dreifuss muscular dystrophy (EDMD) is characterized by muscular weakness and atrophy, with early joint contractures and cardiomyopathy. "ResponseNet also suggested that a problem in the SYNE2 gene, which is known to cause Emery Dreifuss muscular dystrophy, leads to the loss of miR-29 by affecting the MYC transcription regulation complex." (PMID 31114913, 2019).
emphysema (1 paper, 2024). "Reportedly, c-MYC expression in the lung tissue of emphysema mouse models is significantly reduced, and it is believed that c-MYC participates in the occurrence and progression of COPD." (PMID 39138434, 2024).
enteritis (1 paper, 2023). Inflammation of the small intestine. "The results showed that dietary TiO2 NPs markedly prevented the induction of c‐MYC and β‐catenin on day 14 after IR, suggesting that TiO2 NPs inhibited the activation of Wnt signalling during enteritis regeneration." (PMID 36798041, 2023).
eosinophilia (1 paper, 2022). "Unbiased single-cell sequencing analysis of controls and SP-CI73T mutants at a time coordinated with peak eosinophilia (14 days) defined heightened inflammatory activation, chemotaxis, and survival signaling (IL-6, IL-4/13, STAT3, Glucocorticoid Receptor, mTOR, and MYC) in eosinophils." (PMID 35571100, 2022).
epidermoid cyst (1 paper, 2014). "In the present study we have provided a quantitative assessment of c-MYC gene expression for epidermal cysts using RT-QPCR methodology." (PMID 24683550, 2014).
erythroderma (1 paper, 2017). "Genetic biomarkers such as MYC gain at 8q24.21 (40%) and MNT loss at 17p13 (30%) were found useful along with as the demonstration of upregulated expression of STAT4, TWIST1 and DNM3 or PLS3, especially for cases with erythroderma and lack of abnormal phenotype." (PMID 28301507, 2017).
Feingold syndrome type 1 (1 paper, 2018). Feingold syndrome type 1 (FS1) is a rare inherited malformation syndrome characterized by microcephaly, short stature and numerous digital anomalies. "Since miR-17-92 expression is transcriptionally regulated by MYC transcription factors, it has been postulated that Feingold syndrome type 1 and 2 may be caused by a common molecular mechanism." (PMID 29636449, 2018).
food allergy (1 paper, 2018). Gastrointestinal disturbances, skin eruptions, or shock due to allergic reactions to allergens in food. "Gene sets testing revealed that targets of the E2F and MYC TF networks and genes involved in the G2/M cell cycle checkpoint transition were down-regulated among children with food allergy." (PMID 30120223, 2018). "Our analysis of the epigenetically regulated transcriptional response points to gene networks activated via E2F and MYC, and mTOR metabolic programs as markedly altered in children with food allergy and delineates these as key pathways modified by gene–environment interactions." (PMID 30120223, 2018).
gallbladder adenocarcinoma (1 paper, 2023). A carcinoma that arises from glandular epithelial cells of the gall bladder. "Compared to other gallbladder adenocarcinoma without HCG, the proportion of M1 macrophage was at a higher level and the gene sets of MYC targets v1 and PI3K/AKT/mTOR signaling were highly expressed in our case." (PMID 37841278, 2023).
gastrointestinal carcinoma (1 paper, 2017). "In human gastrointestinal carcinoma, defects in the Wnt-APC pathway results in enhanced T-cell factor 4 (TCF4) transcriptional activation of c-MYC." (PMID 29232378, 2017).
germinoma (1 paper, 2024). A malignant germ cell tumor arising in the central nervous system. "Subtype 2, characterized as MYC/E2F type, exhibited enrichment in cell cycle-related pathways and high expression of MYC/E2F target genes, primarily composed of germinomas." (PMID 38790424, 2024).
glaucoma (1 paper, 2023). Increased pressure in the eyeball due to obstruction of the outflow of aqueous humor. "Our data also revealed an obvious dysregulation of MYC and CDKN1A expression in the conjunctiva of glaucoma patients with hyperfibrosis." (PMID 37569323, 2023).
goblet cell adenocarcinoma (1 paper, 2023). "Mutations in the MYC/c-MYC gene, which presumably have a stimulatory effect on its function, are also reported in less than 10% of cases of appendiceal goblet cell adenocarcinoma and mucinous/non-mucinous adenocarcinoma of the appendix, being a secondary mutation in appendiceal cancers." (PMID 37509254, 2023).
Gorlin syndrome (1 paper, 2020). "When the reprogramming factors OCT4/3, SOX2, KLF4 and c-MYC were introduced into 4.0 x 105 cells, iPSCs generated from four patients with Gorlin syndrome were successfully generated and designated as G11-, G12-, G36- and G72-iPSC." (PMID 32436863, 2020).
HCMV infection (1 paper, 2019). "For the case-control analysis, regulation of gene expression (E2F targets, MYC targets), cell signal integration (mTORC1 signalling, PI3K AKT mTOR signalling) and immune response pathways were similarly identified (Browne HCMV infection, Bohn primary immunodeficiency syndrome)." (PMID 31719968, 2019).
hemimegalencephaly (1 paper, 2018). "Increased MYC expression has been reported in hemimegalencephaly, though to our knowledge, mutations in MYC itself have not been shown to drive the pathogenesis of this malformation." (PMID 29745900, 2018).
Hepatosplenomegaly (1 paper, 2021). Simultaneous enlargement of the liver and spleen. "Multivariable analysis showed that age, IPI, red blood cell count, neutrophil count, MYC expression, and hepatosplenomegaly were independent predictors, and the prognostic nomogram was developed." (PMID 34804942, 2021). "IPI, NE, MYC, hepatosplenomegaly, and age proved to be adverse factors for the survival of CD5+ patients." (PMID 34804942, 2021). "Subsequently, we developed a specific nomogram based on the multivariable Cox model, which consisted of six variables: age, IPI, RBC, MYC, hepatosplenomegaly, and NE." (PMID 34804942, 2021).
hyperplastic polyp (1 paper, 2012). A polyp found mainly in the stomach and colon. "In sessile serrated adenomas and hyperplastic polyps, c-MYC expression was detected in the basal third of the crypts." (PMID 23045412, 2012).
hypersplenism (1 paper, 2024). Overactive functioning of the spleen, resulting in excessive destruction of blood cells. "The comprehensive results indicated that patients with hypersplenism showed an induction of macrophage M2-like activation through the MEK-ERK-c-MYC axis." (PMID 39620221, 2024).
Intellectual disability (1 paper, 2022). "Human fibroblast cells from a patient with infantile-onset DM1 and a severe intellectual disability and from a control patient were transformed into iPSCs using the Sendai virus technique employing Yamanaka factors (OCT4, KLF4, MYC, and SOX2)." (PMID 35075265, 2022).
intraductal papillary mucinous neoplasm (1 paper, 2021). "Besides PanIN lesions, ARID1A deficiency could also facilitate intraductal papillary mucinous neoplasm (IPMN) formation through multiple pathways, including MYC-mediated protein synthesis and SOX9/mTOR pathway." (PMID 33983114, 2021).
intraepithelial neoplasia (1 paper, 2012). A precancerous neoplastic process that affects the squamous, glandular, or transitional cell epithelium without evidence of invasion. "In lesions with low grade intraepithelial neoplasia, c-MYC was expressed at low level with very few weakly positive SIRT1 expressing cells distributed throughout the lesions." (PMID 23045412, 2012). "In lesions with high grade intraepithelial neoplasia, c-MYC expression was found at a moderate to high level, whereas SIRT1 expression was restricted to single cells." (PMID 23045412, 2012). "In this group only a subset of mostly high grade intraepithelial neoplasia and carcinoma was characterized by elevated c-MYC and SIRT1 expression." (PMID 23045412, 2012). "Interestingly, in wild type BRAF and KRAS lesions with high grade intraepithelial neoplasia, moderate to strong c-MYC expression correlated with nuclear beta-catenin localization." (PMID 23045412, 2012). "For instance in some lesions with high grade intraepithelial neoplasia and KRAS mutation that displayed high c-MYC and SIRT1 expression, no nuclear beta-catenin was detected, whereas other lesions with equally high c-MYC and SIRT1 levels were positive for nuclear beta-catenin (data not shown)." (PMID 23045412, 2012).
keratoconus (1 paper, 2025). A degenerative, structural disorder of the eye, characterized by a cone-shaped protrusion of the cornea. "As a consequence, down-regulated voltage-gated calcium channels in CACNA1C, CACNA1G, CACNA1D1, and CACNA2D4, and purinergic receptors P2RX1 along with the down- regulated transcription factors including JUN and MYC can be attributed to reduced cell proliferation in keratoconus." (PMID 39420106, 2025).
kidney infection (1 paper, 2025). "In a model of kidney infection, rLon treatment prevented, c-MYC, N-MYC and L-MYC over-expression, MYC-dependent gene expression, specifically renal toxicity genes and pathology, suggesting that rLon recognizes and corrects MYC dysregulation in this disease." (PMID 40000737, 2025).
large cell lung carcinoma (1 paper, 2012). "The same regulatory effects of SOX2 on the expression of WNT1, WNT2, NOTCH1 and c-MYC were also observed in the human large cell lung carcinoma cell line H460 with SOX2 silencing.This finding indicates a universal regulatory mechanism of SOX2 on the oncogene network of both human lung cell lines." (PMID 22615765, 2012).
liver hemangioma (1 paper, 2014). A hemangioma arising from the liver. "This is in line with the lack of tumor-inhibiting properties of atorvastatin in a mouse model of TSC2-related liver hemangioma, but not with data obtained with a MYC-driven HCC mouse model where atorvastatin acted as a tumor-preventive compound." (PMID 25319454, 2014).
male infertility (1 paper, 2024). The inability of the male to effect fertilization of an ovum after a specified period of unprotected intercourse. "Deletion of FBXW7 in germ cells suppresses differentiation by upregulation of MYC and CCNE1 and leads to male infertility, which is similar to the phenotype of Cwf19l2‐SKO mice in this study." (PMID 38889293, 2024).
malignant myoepithelioma (1 paper, 2022). An infiltrating malignant tumor characterized by the presence of atypical cells with myoepithelial differentiation. "MYC gene amplification was detected in one responder patient affected by malignant myoepithelioma, and MYC amplification associated with HEY1 amplification (possibly due to close chromosomal location) was identified in patient TOMAS-34 (non-responder patient affected by uterine LMS)." (PMID 36110934, 2022).
malignant testicular teratoma (1 paper, 2020). "This is consistent with c-MYC overexpression observed in most other human malignancies including ocular MM and malignant testicular teratoma." (PMID 32019273, 2020).
meningeal tumors (1 paper, 2017). "Additionally, FOS, MYC, and PDPN have been shown to be overexpressed specifically in meningeal tumors." (PMID 29073243, 2017).
muscle atrophy (1 paper, 2025). The loss of muscle tissue due to inactivity or disease. "TEAD4, FOS and MYC are essential for embryonic skeletal muscle development, activation of these regulons in RCT implicates the activation of an early developmental program in the pathogenesis of muscle atrophy." (PMID 39435630, 2025).
myocarditis (1 paper, 2022). Myocarditis is a condition that is characterized by inflammation of the heart muscle (myocardium). "In this study, we could discriminate between a clinical group presenting myocarditis with the DCM phenotype (MYC-DCM) and myocarditis without the DCM phenotype (MYC-nonDCM)." (PMID 35877578, 2022).
Myoclonus (1 paper, 2019). Very brief, involuntary random muscular contractions occurring at rest, in response to sensory stimuli, or accompanying voluntary movements. "The noncortical origin of the myoclonus is supported electrophysiologically in 5 genetic disorders presenting with M‐D (MYC/DYT‐SGCE, MYC/DYT‐KCTD17, DYT‐ANO3, ATX‐ATM, ATX‐PRKCG) and unknown in 2 others (CHOR/DYT‐ADCY5 and CHOR‐NKX2‐1)." (PMID 31584223, 2019).
oncocytoma (1 paper, 2014). "Interestingly, MYC is overexpressed in both the benign oncocytoma-like and high-grade oncocytic carcinoma regions." (PMID 25275525, 2014).
optic neuritis (1 paper, 2023). Optic neuritis is inflammation of the optic nerve, the nerve that carries the visual signal from the eye to the brain.The conditionmay cause sudden, reduced vision in the affected eye(s). "The fact that we detected MYC amplification in the CSF in our retrospective analysis suggests that a tumor could have been suspected already upon analysis of CSF, via lumbar puncture performed as diagnostic workup upon suspicion of optic neuritis." (PMID 37173990, 2023).
oral lichen planus (1 paper, 2022). Oral lichen planus is a chronic inflammatory oral condition of unknown aetiology characterized by T-cell-mediated chronic immune response and abnormal epithelial keratinization cycle. "Some studies have already demonstrated a higher rate of MYC gain, polysomy or amplification in OSCC or oral lichen planus that progressed to OSCC than in normal mucosa or lesions that did not progress." (PMID 35884529, 2022).
oropharyngeal cancer (1 paper, 2025). Carcinoma, predominantly squamous cell, arising from the epithelial cells of the oropharynx. "In relation to oral and oropharyngeal cancer, significant associations were observed for a suite of genes including HSPA5, TNFAIP6, AKR1C1, CASP1, ANXA1, and MYC." (PMID 41023518, 2025).
oropharyngeal tumors (1 paper, 2024). "When sequenced FFPE tumors were projected onto tumor states and archetypes, tumors responsive to treatment (purple) clustered in state T2, characterized by EGFR-p63/WNT and downregulation of EMT-ZEB1 and DNA Repair-MYC-E2F, and associated with HPV-positive oropharyngeal tumors." (PMID 38505587, 2024).
ovarian endometriosis (1 paper, 2012). A non-neoplastic disorder characterized by the growth of endometrial tissue in the ovaries. "Dys-regulation of three (CLOCK, ESR1, and MYC) major transcription factors appeared to be significant causative factors in the pathogenesis of ovarian endometriosis." (PMID 23006437, 2012).
Paraproteinemia (1 paper, 2024). An abnormal immunoglobulin or part of an Ig (light chain) in the circulation. "To determine whether the decrease in paraproteinemia following treatment with C3d reflected a decrease in tumor burden, we assayed the frequency of plasma cells in bone marrow retrieved from Vκ*-MYC mice 60 d after treatment with C3d or from paired Vκ*-MYC mice that received PBS only." (PMID 39693340, 2024).
penile squamous cell carcinoma (1 paper, 2015). "It was proposed that c-MYC copy number is associated with poor outcomes in penile squamous cell carcinoma." (PMID 25901368, 2015).
peritoneal cancer (1 paper, 2016). A peritoneum cancer that is located in the inside of the abdomen. "VEGF concentrations in ascites were significantly higher in c-MYC-induced cancer than in the two other types of cancers, suggesting that angiogenesis is responsible for c-MYC-induced peritoneal cancer." (PMID 27483433, 2016).
peritonitis (1 paper, 2016). Inflammation of the peritoneum (tissue that lines the abdominal wall and covers most of the organs in the abdomen). "Secondly, in the present study, we did not assess the therapeutic effects of anti-inflammatory drugs or anti-angiogenic drugs on KRAS- or c-MYC-induced peritonitis." (PMID 27483433, 2016).
pilocytic astrocytoma (1 paper, 2021). Pilocytic astrocytoma is a rare subtype of low-grade glioma of the central nervous system characterized by a well circumscribed, often cystic, brain tumor with a discrete mural nodule and long, hair-like projections that extend from the neoplastic astrocytes. "The analysis of correlation between genes from the MYC and E2F families showed a positive Pearson correlation coefficient in pilocytic astrocytomas, eight out of nine gene–gene pairs achieved statistical significance with r values ranging from 0.55 to 0.81." (PMID 33430425, 2021).